IL6 (interleukin 6)
Diseases named in the same sentence as IL6 in open-access papers (continued):
Sharing a sentence is not in itself a finding about the gene and the disease.
Sepsis (continued). "IL-6 and TNF-α are the critical mediators of sepsis, and their uncontrolled regulation can cause cell death and DNA damage depending on the severity of cytokine production." (PMID 34194518, 2021). "LOX-1 deletion in a murine model of polymicrobial sepsis reduced IL-6 and TNFα levels in the blood and lungs, which enhanced bacterial clearance and prevented neutrophil activation." (PMID 34616409, 2021). "The aim of the study was to conduct a meta-analysis to evaluate the accuracy of neutrophil CD64, procalcitonin (PCT), and interleukin-6 (IL-6) as markers for the diagnosis of sepsis in adult patients." (PMID 33902476, 2021). "In this regard, measurements of serum biomarkers, such as PCT, CRP, interleukin-6, neopterin, and pro-adrenomedullin, are useful in the diagnosis and management of sepsis." (PMID 33810263, 2021). "The severity of cytokine storms associated with severe sepsis, ARDS, and burns is likely caused by endothelial injuries; in patients with these conditions, elevated IL-6 levels are correlated with elevated levels of IL-8, MCP-1, and PAI-132,62,63." (PMID 34253862, 2021). "Further, it has been shown that LPS-induced sepsis substantially upregulates the expression of IL-6 in cardiac tissues through increased production of collagen and causes fibrosis of the heart." (PMID 35005242, 2021). "IL-6 is a biomarker of lethal sepsis, and IL-8 is a neutrophil chemotactic factor, and both cytokines play key roles in lung injury." (PMID 34944016, 2021). "Elevated IL6 and resistin levels correlate with sepsis severity as well as end-organ damage and appear to be associated with increased mortality." (PMID 34884590, 2021). "Biomarker levels of IL-6, PCT and CRP were associated with this composite outcome of sepsis severity, in which PCT had the highest diagnostic accuracy." (PMID 33407770, 2021). "The aim of this study was to evaluate the association of interleukin-6(IL-6), procalcitonin (PCT) and CRP with subsequent sepsis severity and mortality in preterm infants suspected of late onset neonatal sepsis." (PMID 33407770, 2021). "Markers currently in use, such as CRP, PCT, and interleukin 6 (IL-6), were repeatedly found to be compared with each other in the literature review to justify its superiority in diagnosis of sepsis." (PMID 33803628, 2021). "Our results suggest that PEGylated catalase can effectively regulate cytokine production by activated leukocytes, suppress the elevated level of AST, ALT, TNF-α, and IL-6 in mice with induced sepsis, and significantly improve the survival rate of the mice." (PMID 34888304, 2021). "In rats, BER inhibits increasing TNF-α and IL-6 levels induced by multimicrobial sepsis in the intestinal mucosal barrier and increases the level of tight junction proteins and permeability of epithelial cells." (PMID 34712727, 2021). "In sepsis models, miR-128-3p overexpression decreased pro-inflammatory factors IL-6 and IL-1β’s expression as well as inhibited apoptosis indicator caspase-3 transcriptive activity." (PMID 34430706, 2021). "In patients with severe sepsis and septic shock; IL‐1β, IL‐6, and G‐CSF have demonstrated good accuracy for predicting early mortality while IL‐6 and G‐CSF showed to be predictive of worsening of organ dysfunction." (PMID 33719215, 2021). "The results of this study showed that gut-origin sepsis was associated with increased expression of the proinflammatory cytokines (TNF-α, IL-1β, IL-6, and HMGB1) and decreased expression of anti-inflammatory cytokine IL-10." (PMID 34790828, 2021). "The use of CRP and IL-6 as biomarkers of sepsis or infection after solid organ Tx is therefore doubtful, and PCT should be used with caution only in specific groups of patients (e.g., induction immunosuppression with basiliximab and rituximab)." (PMID 33505219, 2021).
Sepsis (continued). "The present study found that inhibition of mitochondrial division alleviated sepsis-induced inflammation, including the release of cytokines TNFα and IL-6, and the phosphorylation of NF-κB." (PMID 34566637, 2021). "Ulinastatin, a human protease inhibitor and androstenediol, a metabolite of dihydroxystheniandrosterone, reduce plasma levels of TNF-α and IL-6 in rats with sepsis." (PMID 34577795, 2021). "Hemoperfusion can decrease IL-6 and IL-8 levels in patients with sepsis and can decrease the mortality rate." (PMID 34490065, 2021). "The reduced pathology of sepsis-caused ALI was correlated with reduced levels of pro-inflammation cytokines such as TNF-α, IL-6 and IL-1β in blood and their mRNA transcriptional level directly in lung tissue." (PMID 33842398, 2021). "Administration of tannic acid decreased the level of IL-6 in testicular tissue compared with the sepsis group (0.77 ± 0.01 vs 1.65 ± 0.01 %, P<0.05)." (PMID 35317115, 2021). "More importantly, suppression of NF-κB contributed to a reduction of release of LPS-induced pro-inflammatory cytokines such as TNF-α, IL-1β, and IL-6 in sepsis." (PMID 33413595, 2021). "Among cytokines, IL-6 serves as an important mediator during the acute phase of response to inflammation in sepsis, and its clinical value has been assessed in patients with various septic conditions in several studies." (PMID 34460840, 2021). "The IL-6 level gradually decreased from 40 ng/mL at 6 h after sepsis to 35 ng/mL at 24 h after sepsis." (PMID 33946773, 2021). "Partial depletion of Tregs elevated IL-17A, IL-1β, and IL-6 production and decreased IL-10 levels, leading to lower bacterial load and attenuation of lung injury in secondary P. aeruginosa infection after sepsis." (PMID 34222495, 2021). "PEGylated catalase can effectively regulate the cytokine production by activated leukocytes, suppress the elevated level of AST, ALT, TNF-α, and IL-6 in mice with induced sepsis, and significantly improve the survival rate." (PMID 34888304, 2021). "The mRNA and protein expressions of IL-1β and IL-6, two main pro-inflammatory factors, were both higher in mice with sepsis than in the sham group." (PMID 34430706, 2021). "A bedside IL-6 test, however, was less sensitive for identifying early-onset as compared to late-onset sepsis cases." (PMID 34640557, 2021). "In-vitro decreased T-cell apoptosis, potentiated monocytic LPS-induced TNF-α and IL-6 production from sepsis patients." (PMID 33920518, 2021). "In the pathophysiology of sepsis, the proinflammatory cytokine IL-6 is known to play a pivotal role and is an overproduced cytokine that causes hypercytokaemia." (PMID 35069560, 2021). "Tumor necrosis factor alpha, IL-6, and IL-1β are significant pro-inflammatory factors, which can lead to and promote the occurrence and development of sepsis." (PMID 34616305, 2021). "In prWAT, the main effects of CLP-induced sepsis included increased expression of proinflammatory cytokines (Tnf and IL-6) and a neutrophil marker (Ltf) and decreased markers of adipogenesis." (PMID 34322037, 2021). "Of the three biomarkers studied, neutrophil CD64 showed the highest diagnostic value for sepsis, followed by PCT, and IL-6." (PMID 33902476, 2021). "Our findings show that serum IL-6 and PCT levels at moment of suspected late onset neonatal sepsis offer valuable information about sepsis severity and mortality risk in infants born below 32 weeks of gestation." (PMID 33407770, 2021). "Most immunoassays find that concentrations of IL‐6 in normal plasma are undetectable or range between 10 and 75 ng L−1, with levels rising to 1–2 μg L−1 in sepsis or, exceptionally to 200 μg L−1 in meningococcal disease." (PMID 34114369, 2021). "We also observed that administering IL-38 to mice with CLP-induced sepsis lowered the circulating concentrations of the proinflammatory cytokines IL-1β, IL-6, and TNF-α, while elevating systemic levels of the anti-inflammatory cytokine IL-10." (PMID 34955683, 2021).
Sepsis (continued). "In severe sepsis, however, several proinflammatory cytokines (including IL-1, IL-6 and TNF-α), induced by endotoxins, lipopolysaccharides and other infectious mediators, promote the generation and release of procoagulant tissue factor of endothelial cells." (PMID 33654698, 2021). "TNF-α, IL-6, and IL-1β are all important proinflammatory factors, which play an important role in the occurrence and development of sepsis." (PMID 34721636, 2021). "Compared with a low concentration of IL-6 in the normal condition (lower than 10 pg/mL), the level of IL-6 rises rapidly (even more than 1 pg/ml) when sepsis occurs in adults." (PMID 34281552, 2021). "As determined by clinical and laboratory characteristics, IL-6 concentrations correlate with the severity of sepsis." (PMID 34684298, 2021). "As a promising biomarker for sepsis, higher IL‐6 concentration correlates with the severity of sepsis." (PMID 33369167, 2021). "In this large retrospective study, we assessed the association between IL-6, PCT and CRP at onset and subsequent sepsis severity and mortality." (PMID 33407770, 2021). "IL-6 contributes to systemic inflammation in critical illness and sepsis, and it increases protein breakdown and skeletal muscle atrophy." (PMID 34572540, 2021). "In a sepsis model, pioglitazone reduced LPS-induced TNFα and IL-6 production from mouse macrophages through inhibition of NFκB." (PMID 34831270, 2021). "Sepsis patients exhibited significantly higher expression and production of NLRP3 and the proinflammatory cytokines (TNF-α, IL-6 and IL-1β) than healthy controls, and these levels were significantly increased with sepsis progression." (PMID 34172780, 2021). "The expression of Tnf and IL-6 genes is widely used to characterize sepsis-induced inflammatory response in several tissues." (PMID 34322037, 2021). "Many biomarkers such as procalcitonin (PCT) or interleukin (IL)-6 or IL-18 are used in clinical practice to facilitate the diagnosis of sepsis." (PMID 34577843, 2021). "CRP is an acute phase reactant, and increased circulating CRP levels follow rising levels of cytokines (e.g., interleukin-6, tumor necrosis factor-a), which are sustained in the course of sepsis." (PMID 34439240, 2021). "Our results showed that either LPS injection or CLP surgery significantly up‐regulated the levels of circulating TNF‐α, IL‐1β, IFN‐γ and IL‐6 in mice, indicating successful establishment of sepsis mouse model." (PMID 33982381, 2021). "These factors should be comprehensively considered for a better understanding of sepsis when IL-6 levels are elevated." (PMID 33446739, 2021). "The expression of IL-1β, IL-6, and IL-18 in lung tissues of sepsis-induced ALI mouse model was obviously decreased by the infection of lv-LBH (P < 0.001)." (PMID 33553423, 2021). "Animal studies have shown that remote ischemic conditioning and postconditioning attenuated inflammatory responses, including IL-6 levels, and improved survival outcomes in sepsis." (PMID 33829305, 2021). "Many pro-inflammatory cytokines, including IL-1, IL-6, IL-12, and IL-17, play critical roles during early sepsis." (PMID 34884813, 2021). "The results showed that at 6 h after sepsis, except for IL-6, TNF-α, IL-1β, and IL-10 levels decreased in DEX-treated mice." (PMID 33981237, 2021). "For instance, after a rapid increase of IL-6 the levels also decrease rapidly and provide less information on future clinical course compared to determining IL-6 early in sepsis." (PMID 33407770, 2021). "It has been shown that increased pro-inflammatory cytokine levels such as TNFα and IL-6 levels correlate with poor outcome in sepsis; however, their routine clinical utility remains questionable." (PMID 34830673, 2021). "IgM levels did not correlate with albumin (r = 0.058, p = 0.73), or immune markers TNFα (r = −0.027, p = 0.86), IL-1 (r = 0.1292, p = 0.91), IL-6 (r = −0.1615, p = 0.30), or IL-8 (r = −0.0209, p = 0.89) in the sepsis cohort." (PMID 34830673, 2021).
Sepsis (continued). "In vivo, overexpression of LBH decreased the lung histological changes, lung injury score, lung W/D ratio, expression of IL-1β, IL-6, and IL-18, and activation of NLRP3inflammasome in lung tissues of sepsis-induced ALI mouse model." (PMID 33553423, 2021). "Because acute IL-6 levels correspond to mortality and morbidity in sepsis, inhibiting plasma IL-6 using MSCs on the SF nanofibers contributed to the enhanced survival rate of septic mice." (PMID 33946773, 2021). "In the regulation of cytokine production, some cytokines had been proved to be beneficial for the control of sepsis, such as the anti-inflammatory cytokines of IL-1Ra, IL-4, IL-6, IL-10, IL-11, IL-13, IL-35, and TGF-β." (PMID 34938184, 2021). "Since an imbalance between the pro- and anti-inflammatory systems is considered to be a vital mechanism of sepsis, we measured the levels of pro-inflammatory cytokines including IL-6, TNF-α, and HMGB1 in the kidneys." (PMID 33936050, 2021). "TRAF6 is closely related to ALI caused by sepsis, and overexpression of TRAF6 increases the expression levels of TNF-α and IL-6." (PMID 34602057, 2021). "The levels of other inflammatory mediators most relevant in sepsis, including TNFa, Il-6, and Il-1b, while increased in our model of CLP, remained unchanged upon SCH772984 treatment." (PMID 34638546, 2021). "In these studies, RIC reduced the levels the proinflammatory cytokines TNF-α, IL-1β, and IL-6, as well as suppressing the sepsis-induced increase in plasma cardiac troponin I." (PMID 34169381, 2021). "Macrophage-mediated inflammation releases cytokines such as TNF-α, IL-1β, IL-6, and IL-8, which play an important role in the pathogenesis of sepsis." (PMID 34220338, 2021). "Early biomarkers, such as IL-6, were found to be significantly upregulated as early as two days before clinical diagnosis of sepsis." (PMID 34640557, 2021). "For instance, an early bolus followed by infusion of DFO was sufficient to completely block IL-6 and ROS generation in a sepsis-like syndrome with multiorgan dysfunction following acute hepatic ischemia." (PMID 33466819, 2021). "Previous studies reported that IL-6 was determined to be a promising target molecule for systemic inflammatory response syndromes such as sepsis." (PMID 34960054, 2021). "Elevation of serum IL-6 and IL-10 levels has been reported in the initial phase of the immune response to sepsis." (PMID 34793546, 2021). "IL-6 acts as a major cytokine has both pro-inflammatory and anti-inflammatory effects and is involved in the stress response to surgical trauma, sepsis, and burns." (PMID 34801038, 2021). "The observed longitudinal changes of plasma lEVs concentration is similar to many biologically active compounds with elevated levels during sepsis (e.g., c-reactive protein, interleukin 6)." (PMID 34604260, 2021). "Plasma acetylcarnitine has a positive correlation with plasma IL-6, IL-8, and IL-10 as well as sepsis severity in patients." (PMID 34087197, 2021). "Uncontrolled inflammation leads to increase in proinflammatory cytokines such as tumor necrosis-alpha (TNF-α) and interleukin-6 (IL-6), and it plays a critical role in sepsis pathogenesis." (PMID 34575154, 2021). "The anti-inflammatory activity of rhPRG4 was also demonstrated in an in vitro sepsis model, where rhPRG4 at 50 or 100μg/mL reduced interleukin-6 (IL-6) secretion from murine and human endothelial cells." (PMID 34992596, 2021). "Consecutively, the moderate sepsis group had significantly higher IL-6 levels as well as SRSS Scores indicating a more severe sepsis manifestation and is comparable to other experimental sepsis studies." (PMID 34555053, 2021). "This is promising given the finding that increased IL-6 and TNF-a in the plasma and bronchoalveolar lavage (BAL) fluid in sepsis correlates with decreased survival and that higher IL-6 equates to longer time spent on a ventilator." (PMID 35011653, 2021).
Sepsis (continued). "High levels of IL-6 have been reported in acute conditions such as sepsis, and it is an excellent predictor of disease severity that mediates acute phase response." (PMID 33803665, 2021). "The statistical analysis indicated that, compared with those in the sham group, IL-1β, TNFα, IL-6, and IFNγ levels in the Sepsis group were upregulated, while SOD and GSH-PX levels were downregulated." (PMID 34489703, 2021). "Across all neonates, relative expression levels of MYD88 (p < 0.001), NFKB1 (p < 0.001), and IL6 (p = 0.027) were significantly higher in sepsis cases compared to controls." (PMID 34183713, 2021). "While infection by the severe acute respiratory syndrome-associated coronavirus (SARS-CoV-2) induces dose-dependent IL-6 production from bronchial epithelial cells, the role of IL-6 to detect sepsis, particularly in viral infection, remains inconclusive." (PMID 33803628, 2021). "Reportedly, treatment with IL-34 also assisted to protect mice against polymicrobial sepsis by inducing the expression of cytokines (IL-6, TNFα) and chemokines (CXCL1, CCL2)." (PMID 32231137, 2020). "Recent several studies have included many sepsis markers, like C-reactive protein (CRP), procalcitonin (PCT), and interleukin-6 (IL-6) to improve sepsis diagnosis." (PMID 33061986, 2020). "The median concentration of IL-6 among proven sepsis (1612 pg/mL) was significantly higher than that of the clinical sepsis (138 pg/mL) and control groups (57 pg/mL) (p < 0.001)." (PMID 33233806, 2020). "MiR-192-5p negatively correlated with concentrations of pro-inflammatory cytokines (IL-6, IL-1 and IL-8) and sepsis markers (e.g., CRP)." (PMID 32993185, 2020). "By contrast, previous studies have demonstrated that the MSCs significantly reduced systemic cytokines and chemokines (IL-6, IL-1b, IL-10, KC, and CCL5) after 28 h of administration in the sepsis-associated inflammation mouse model." (PMID 32903481, 2020). "Specifically, TNF-α and MIP-2 are primary cytokines known to trigger a variety of clinical manifestations of LPS-induced sepsis, whereas IL-6 levels correlate to a poor outcome and multiple organ failure in septic patients." (PMID 32353952, 2020). "In a mouse model study of sepsis-induced AKI, IL-6 depletion diminished neutrophil infiltration and caused resistance to renal injury." (PMID 33317643, 2020). "It has been shown that higher IL-6 and TNF-α levels are associated with a higher risk of developing sepsis, and that, among patients with sepsis, men had worse outcomes, higher TNFα, and lower IL-10 levels than women." (PMID 32485823, 2020). "Release of the proinflammatory cytokines interleukin- (IL-) 1β and IL-6 and immunomodulatory cytokine IL-10 by innate immune cells including macrophages, granulocytes, and natural killer (NK) cells during sepsis is well documented." (PMID 32273831, 2020). "Among the pro-inflammatory cytokines studied during sepsis, IL-1β, IL-6, IL-12, and IL-17 are of crucial importance." (PMID 32895405, 2020). "Its role in the inflammatory process has been recently studied in an in vitro model of sepsis where inhibition of miR-155-5p reduced the expression of IL-6 and IL-8 as pro-inflammatory cytokines by 31% and 14%, respectively." (PMID 32993185, 2020). "Sepsis scores were thus found to be in strong linear correlation with the concentrations of IL-6, IFNγ, and TNFα and again, higher sepsis scores in mice with pre-existing CIA correlated with elevated levels of these cytokines." (PMID 33117382, 2020). "In the patient with sepsis, IL-6 and TNF-α were significantly attenuated during H2 gas inhalation and increased after its discontinuation." (PMID 33041520, 2020). "IL-6 levels were found to be significantly elevated in the proved sepsis group than suspected neonatal sepsis cases (p=0.004)." (PMID 33061986, 2020). "Previous findings confirmed that the level of TNF-α, IL-1β, and IL-6 are elevated within 6 h in sepsis brain tissue and continually increased for 10 to 30 days." (PMID 32457609, 2020).